CIP2A (cellular inhibitor of PP2A)
Diseases named in the same sentence as CIP2A in open-access papers (continued):
Sharing a sentence is not in itself a finding about the gene and the disease.
colorectal cancer (17 papers, 2013 to 2025). A primary or metastatic malignant neoplasm that affects the colon or rectum. "Our previous study in colorectal cancer cell lines revealed that the KRAS G12D mutation decreased the impact of CIP2A on downstream effectors of the EGFR signaling pathway, when cells were treated with temsirolimus." (PMID 25896895, 2015). "In conclusion, the results of this study show that CIP2A is associated with colorectal cancer related survival." (PMID 24098375, 2013). "Similar mechanisms have been reported in multiple myeloma and colorectal cancer, where CIP2A silencing decreases p-AKT and increases drug sensitivity." (PMID 40943297, 2025). "Another protein, cancer inhibitor of protein phosphatase 2A (CIP2A), has increased expression levels in colorectal cancer, stomach cancer, prostate cancer, and multiple myeloma." (PMID 34440124, 2021). "CIP2A is overexpressed in colorectal cancer (CRC), and its expression levels are an independent marker for long-term outcome of CRC." (PMID 33078202, 2021). "In 2018, we revealed that Eth can induce inhibitory effects and downregulate the oncoprotein CIP2A (cancerous inhibitor of protein phosphatase 2A) in colorectal cancer cells." (PMID 31969821, 2019). "We found that CIP2A expression was positively correlated with ATF6 expression by analyzing publicly available RNA sequence data of patients with colorectal cancer (The Cancer Genome Atlas, TCGA)." (PMID 30063110, 2018). "Suppression of CIP2A transcription by siRNA was found to sensitize colorectal cancer cells to irradiation and decrease their survival in vitro." (PMID 29441695, 2018). "The effects of CIP2A knockdown by siRNA on cell survival were further investigated in colorectal cancer cells exposed to radiation." (PMID 29441695, 2018). "We investigated the impact of KRAS on CIP2A expression in colorectal cancer patients after colorectal liver metastasectomy." (PMID 25896895, 2015). "We further analysed CIP2A mRNA levels in an independent set of 104 colorectal cancer tissue samples using an RT-QPCR approach." (PMID 24098375, 2013). "The PP2A inhibitory protein CIP2A is increased in colorectal cancer and HCC, accompanied by impaired PP2A activity." (PMID 24307892, 2013). "Histone deacetylase 1 (HDAC1) regulates CIP2A/p90 gene expression in colorectal cancer cells." (PMID 36911405, 2023). "In addition, siRNA inhibition of CIP2A transcription can make colorectal cancer cells sensitive to radiation and reduce their survival rate in vitro." (PMID 36911405, 2023). "Their study indicated that CIP2A may be used as a potential predictive marker of metastasis, prognosis and therapeutic target in colorectal cancer." (PMID 25015035, 2014). "Expression of CIP2A mRNA was initially assessed using expression data sets derived from a published microarray analysis, which was originally performed to identify prognostic markers for colorectal carcinomas according to the lymph node metastasis status." (PMID 24098375, 2013). "However, the functions of CIP2A in colorectal cancer (CRC) and its underlying mechanisms of action are not yet completely understood." (PMID 32321509, 2020). "In addition, CIP2A may be a promising therapeutic target in the development of therapies for colorectal cancer." (PMID 24098375, 2013). "Therefore, CIP2A represents a new prognostic factor in the diagnosis of colorectal cancer." (PMID 24098375, 2013). "The inhibition of HDAC1 by (S)-2 downregulated the transcription of CIP2A/p90 and unleashed PP2A activity, thereby inducing growth arrest and apoptosis in colorectal cancer cells." (PMID 36911405, 2023). "This study aimed to investigate the prognostic value of CIP2A (cancerous inhibitor of protein phosphatase 2A) and the NLR (neutrophil–lymphocyte ratio) in the serum of patients with CRC (colorectal cancer) after resection." (PMID 34144694, 2021).
colorectal cancer (continued). "Cancerous inhibitor of protein phosphatase 2A (CIP2A) is a recently identified oncoprotein that is overexpressed in several malignancies, including leukemia, breast, gastric, prostate, lung, ovarian, head and neck carcinoma, and colorectal cancer." (PMID 25896895, 2015). "Our results show that depletion of CIP2A expression in colorectal cancer cells does not affect Akt signalling, in contrast to observations in HCC cells." (PMID 24098375, 2013). "CIP2A protein levels were very low in human epidermal keratinocytes, nontumorigenic mouse embryo fibroblasts, and immortalized NIH3T3 mouse fibroblasts, but CIP2A was overexpressed in HeLa cells, HT-1080 fibrosarcoma cells, head and neck squamous cell carcinoma and colorectal cancer." (PMID 30341686, 2018).
non-small cell lung carcinoma (14 papers, 2011 to 2025). A group of at least three distinct histological types of lung cancer, including non-small cell squamous cell carcinoma, adenocarcinoma, and large cell carcinoma. "In other studies, overexpressed CIP2A correlated with poor prognosis in non-small cell lung cancers." (PMID 25015035, 2014). "Kaplan-Meier survival analysis showed that the overall survival times in patients expressing either CIP2A or survivin protein in non-small cell lung cancers were shorter." (PMID 25015035, 2014). "CIP2A expression in non-small cell lung cancers correlated with TNM stage, while survivin expression correlated with TNM stage and lymph node metastasis." (PMID 25015035, 2014). "The expression of CIP2A protein was an independent prognostic factor for non-small cell lung cancers patients (COX regression analysis)." (PMID 25015035, 2014). "A potential marker is oncoprotein cancerous inhibitor of PP2A (CIP2A), which acts as a prognostic marker in gastric and non-small cell lung cancers." (PMID 21610708, 2011). "CIP2A is overexpressed in many human cancers, including small and non-small cell lung cancers." (PMID 41155727, 2025). "CIP2A has been identified as a prognostic marker in non-small cell lung cancer, as its expression was higher in lung tumor tissue compared to corresponding normal tissue, and high levels of the protein in tumor samples were associated with reduced overall survival." (PMID 33804833, 2021). "Recently CIP2A has been targeted by a natural compound celastrol in non-small-cell lung cancer." (PMID 25015035, 2014). "Therefore CIP2A expression in non-small cell lung cancers patients may be an useful biomarker of malignancy." (PMID 25015035, 2014). "In addition, CIP2A, an endogenous inhibitor of PP2A, is upregulated in many cancer cells, including non-small cell lung cancer (NSCLC) cells." (PMID 36479072, 2022). "Progress has been made by using small interference RNA (siRNA) to knock down CIP2A expression in breast cancer cells and NSCLC (non-small cell lung cancer) cells, both decreasing the tumorigenic potentials of the cancer cells and sensitizing them to chemotherapy." (PMID 25334061, 2014).
cervical carcinoma (13 papers, 2011 to 2023). A carcinoma arising from either the exocervical squamous epithelium or the endocervical glandular epithelium. "In cervical cancer, CIP2A was found to associate with H-Ras to promote epithelial-mesenchymal transition, resulting in increased migration and invasion of cervical cancer cells in vitro and in vivo." (PMID 31214504, 2019). "Recently, we showed that CIP2A was overexpressed in cervical cancer, and its expression was associated with tumor progression." (PMID 25650660, 2015). "As well, CIP2A protein level was found positively associated with HPV-16E7 level in cervical cancer tissue." (PMID 25650660, 2015). "The binding of Ets1 and Elk1 together to the proximal CIP2A/p90 promoter is absolutely required for CIP2A/p90 expression in liver, endometrial, and cervical carcinoma cells." (PMID 36911405, 2023). "To further verify the regulation and function of CIP2A in cervical cancer cells, we introduced HPV‐16–positive SiHa cells." (PMID 29893470, 2018). "We previously showed a positive association of CIP2A and HPV-16E7 immunoreactivity, and HPV-16E7 depletion in cervical cancer SiHa cells significantly reduced CIP2A expression." (PMID 25650660, 2015). "Our previous study showed that CIP2A was overexpressed in cervical cancer and positively related with HPV-16E7 expression." (PMID 25650660, 2015). "Cancerous inhibitor of protein phosphatase 2A (CIP2A) is a recently identified oncoprotein that is overexpressed in many human malignant tumors including cervical cancer." (PMID 25650660, 2015). "CIP2A was overexpressed in cervical cancer and its expression was upregulated by human papillomavirus 16 E7 oncoprotein." (PMID 25015035, 2014). "In cervical cancer, CIP2A functioned as an oncogene to regulate c-MYC degradation through inhibiting PP2A." (PMID 23342256, 2012). "Additionally, cervical cancer tissue had higher CIP2A mRNA levels compared to healthy adjacent tissue." (PMID 31214504, 2019). "Furthermore, depletion of CIP2A also showed anti-tumorigenic potential in ovarian and cervical cancer cells." (PMID 31214504, 2019). "Furthermore, cervical cancer tissue analysis revealed that CIP2A expression correlated with lymph node metastasis and high-grade and advanced stage cervical cancer." (PMID 31214504, 2019). "Additionally, in cervical cancer, the transcription factor E2F1 has also been implicated in the regulation of CIP2A expression via the E7 oncoprotein." (PMID 31214504, 2019). "Increased CIP2A expression levels have also been reported in cervical cancer." (PMID 31214504, 2019). "The data further hint that CIP2A may be involved in the G1 checkpoint by regulating Cdk1 and Cdk2 in a B‐Myb–dependent manner in cervical cancer cells." (PMID 29893470, 2018). "However, much effort is needed for translational medicine and clinical application of targeting CIP2A for cervical cancer diagnosis and treatment." (PMID 29893470, 2018). "Our previous data showed that CIP2A was overexpressed in cervical cancer." (PMID 29893470, 2018). "To explore whether the upregulation of CIP2A by HPV-16E7 was type-specific, we examined its expression in cells expressing HPV-58E7, the third most common HPV type associated with cervical cancer in Eastern Asia." (PMID 25650660, 2015). "The human papillomavirus 16E7 oncoprotein upregulates CIP2A in cervical cancer." (PMID 24098375, 2013). "Furthermore, five cervical cancer cell lines harbored elevated CIP2A levels." (PMID 31214504, 2019). "However, how CIP2A is regulated by E7 and the role of CIP2A in E7-expressing cells and in the pathogenesis of cervical cancer are unknown." (PMID 25650660, 2015). "The expression of the three putative protein biomarkers we evaluated, i.e., B-MYB, CIP-2A, and TKTL1, was known to increase in histopathology sections of CIN2+ and of cervical carcinoma cones." (PMID 31001477, 2019).
cervical carcinoma (continued). "CIP-2A is overexpressed in cervical carcinomas as it positively correlates with HPV-16 E6 and E7 proteins expression in CIN3 and cervical cancer tissues and cells." (PMID 31001477, 2019). "The first group comprises type I endometrioid EC, ovarian and cervical cancers and is characterized by PP2A inactivation mainly via CIP2A or PME-1, and perhaps also via SET." (PMID 31214504, 2019). "Importantly, recent studies show that CIP2A is over-expressed in various human malignancies including head and neck squamous cell carcinoma, oral squamous cell carcinoma, oesophageal squamous cell carcinoma, colon, gastric, breast, prostate, tongue, lung, cervical cancer and acute myeloid leukaemia." (PMID 22075943, 2011). "Moreover, other transcriptional factors, such as Elk1 and Ets1, have been reported to control CIP2A gene expression in cervical cancer, endometrial carcinoma, and triple‐negative breast cancer." (PMID 30063110, 2018). "The data strongly indicated that only CIP2A (but not PP2A or c-MYC) is a reliable biomarker for detection of cervical cancer and furthermore there was no strong correlation of CIP2A expression with HPV subtype, age, ethnical background, or other patient characteristics." (PMID 25015035, 2014).
head and neck squamous cell carcinoma (13 papers, 2011 to 2022). A squamous cell carcinoma that arises from any of the following anatomic sites: lip and oral cavity, nasal cavity, paranasal sinuses, pharynx, larynx, and salivary glands. "Recently, high CIP2A expression has also been indicated to contribute to radioresistance in head and neck squamous cell carcinoma, but few studies have examined the connection between CIP2A and radiation response regarding other malignancies." (PMID 29441695, 2018). "CIP2A-mediated AKT activation also plays a role in bortezomib-induced apoptosis in head and neck squamous cell carcinoma." (PMID 25015035, 2014). "To clarify the possible clinical importance of CIP2A and Oct4 in HNSCC, we studied CIP2A and Oct4 expression in 52 head and neck squamous cell carcinoma (HNSCC) patient samples by immunohistochemistry." (PMID 25474139, 2015). "CIP2A is overexpressed in several different cancer types including head and neck squamous cell carcinoma (HNSCC), colon-cancer and CML, a subset of myleodysplasic syndromes, and osteosarcoma as well as others." (PMID 25642418, 2014). "We have selected three organ type cancers with higher percentage of changes in CIP2A including lung squamous cell carcinoma, ovarian serous cystadenocarcinoma and Head and Neck squamous cell carcinoma in the context of clinical attributions and tabulated the changes in CIP2A (KIAA1524) gene." (PMID 25015035, 2014).
chronic myeloid leukemia (12 papers, 2011 to 2026). "One of these isoforms, known as novel CIP2A variant (NOCIVA) was isolated from chronic myeloid leukemia (CML) cohorts." (PMID 34944633, 2021). "Previous studies have shown that aberrant expression of CIP2A is associated with progressive diseases in a number of other human malignancies including breast, tongue, lung, gastric, head and neck cancers and chronic myeloid leukaemia." (PMID 22075943, 2011). "Since CIP2A can be used as a marker for the pathogenesis of chronic myelocytic leukemia, our results showed that there was an impact of treatment on the relative expression fold for the CIP2A gene." (PMID 36078884, 2022). "In chronic myeloid leukemia cell line K562, CIP2A augments mitochondrial respiration." (PMID 38321019, 2024). "CIP2A and SET are endogenous inhibitors of the phosphatase 2A (PP2A), a tumor suppressor protein that is recurrently inactivated in acute and chronic myeloid leukemias." (PMID 32110991, 2020). "Cancerous inhibitor of protein phosphatase 2A (CIP2A) is a predictive biomarker of disease progression in many malignancies, including imatinib-treated chronic myeloid leukemia (CML)." (PMID 26987906, 2016).
ovarian carcinoma (11 papers, 2011 to 2025). A malignant neoplasm originating from the surface ovarian epithelium. "To address the role of CIP2A in ovarian cancer, we investigated the association of CIP2A protein expression to clinicopathological variables and molecular markers in serous ovarian cancer." (PMID 21897396, 2011). "Our results show that CIP2A associates with reduced survival and parameters associated with high grade in ovarian cancer patients, and may thus be one of the factors that identify aggressive subtype (type II) of this disease." (PMID 21897396, 2011). "This study provided a deeper insight into the role of CIP2A in ovarian cancer making use of a wide repertoire of approaches." (PMID 40594400, 2025). "In serous ovarian cancers, strong CIP2A immunoreactivity correlated with worse prognosis, and the same was observed in a retrospective study on 152 ovarian cancer specimens, including serous, endometrioid, mucinous, and clear cell subtypes." (PMID 31214504, 2019). "Specifically, for gynecologic cancers, several studies reported on the prognostic potential of CIP2A in cervical and ovarian cancer." (PMID 31214504, 2019). "Another retrospective study of 152 ovarian cancer specimens (serous, endometrioid, mucinous and clear cell) further corroborated this by showing CIP2A overexpression in 65.79% of samples tested." (PMID 31214504, 2019). "In accordance with previous reports, CIP2A knockdown increased the proportion of ovarian cancer cells in the G1 phase and decreased that in the S phase, so CIP2A regulated cell cycle progression at the G1/S boundary." (PMID 25650660, 2015). "CIP2A is overexpressed in human ovarian cancer and its expression has been found to regulate cell proliferation and apoptosis." (PMID 25015035, 2014). "Strong cytoplasmic CIP2A immunopositivity predicted poor outcome in ovarian cancer patients (P<0.0001, log-rank test)." (PMID 21897396, 2011). "In this study, we found that strong cytoplasmic expression of CIP2A in ovarian cancer patients is a marker of reduced overall and progression-free survival." (PMID 21897396, 2011). "In ovarian cancer cell lines, CIP2A protein was expressed to a high extent in both cytoplasmic and nuclear protein fractions." (PMID 21897396, 2011). "Furthermore, CIP2A overexpression conferred resistance to chemotherapy in several solid tumor types, including cervical and ovarian cancers." (PMID 31214504, 2019). "Moreover, CIP2A has been shown to influence response to therapy in breast and ovarian cancers 9,16,17." (PMID 25663244, 2015). "CIP2A nuclear-negative patients had a 5-year ovarian cancer-specific survival of 37.2% (95% CI 30.3–44.2), whereas it was 45.0% (95% CI 39.2–50.8) for those who showed nuclear positivity (P=0.013, log-rank test)." (PMID 21897396, 2011).
leukemia (10 papers, 2011 to 2018). A malignant (clonal) hematologic disorder, involving hematopoietic stem cells and characterized by the presence of primitive or atypical myeloid or lymphoid cells in the bone marrow and the blood. "Their study revealed that CIP2A plays a major role in mediating bortezomib-induced apoptosis in leukemia cells." (PMID 25015035, 2014). "Cancerous Inhibitor of PP2A (CIP2A) was first described as a fusion protein detected in a leukemia patient, which is an endogenous PP2A inhibitor that has been shown to have both proto-oncogenic and prognostic value in cancer." (PMID 25642418, 2014). "The apoptotic effect of bortezomib is also described in leukemia cells by downregulation of CIP2A and upregulation of PP2A activity." (PMID 24307892, 2013). "CIP2A regulates bortezomib-induced apoptosis in leukemia cells." (PMID 25015035, 2014). "CIP2A is reported to be a target of bortezomib in many kinds of malignancies, such as HCC, leukemia, human triple negative breast cancer, and head and neck squamous cell carcinoma." (PMID 24307892, 2013). "This analysis revealed M6 subtype of acute myeloid leukemia as a cancer type in which CIP2A and representative genes of each level of the pathway (EGFR, MEK2 and ETS1) were significantly upregulated in two different genome wide leukemia studies." (PMID 21445343, 2011).
head and neck cancer (9 papers, 2011 to 2024). A primary or metastatic malignant neoplasm affecting the head and neck. "The role of LINC00665 and its micro-peptide CIP2A-BP have yet to be studied in head and neck cancer." (PMID 39595048, 2024). "In addition, the expression of CIP2A in immortalized cell line is an alternative evidence that CIP2A can be present in pre-malignant tissue that CIP2A was present in pre-malignant tissue in the mouse studies as well as the in the patients’ tissues of head and neck cancer." (PMID 26560124, 2015). "Summarizing, although BTZ confers single agent activity against HNSCC cells in vitro and in vivo by inhibition of CIP2A, clinical trials with BTZ in head and neck cancer showed poor results, conceivably by induction of protective autophagy and overexpression of CIP2A." (PMID 29184971, 2018).